SHC1 (SHC adaptor protein 1)
Diseases named in the same sentence as SHC1 in open-access papers (continued):
Sharing a sentence is not in itself a finding about the gene and the disease.
cancer (continued). "Among the genes affected by RRBP1, UBE2C, SHC1, and CLDN7 have all been recently identified as highly relevant targets in other cancers." (PMID 34445467, 2021). "Next, we found copy number variations of MAP2K6, SHC1, and RAC1 in most cancer tissues." (PMID 36969076, 2023). "Furthermore, the SHC1 mRNA levels correlated to pathological stage of COAD, THCA, LUAD, PAAD, KICH, and KIRP cancer (p < 0.05)." (PMID 35601500, 2022). "Taken together, these results strongly suggested that the SHC1 gene was abnormally regulated in multiple cancers as opposed to normal tissues." (PMID 35601500, 2022). "MiR-5582-5p by targeting GAB1, SHC1, and CDK2 could induce apoptosis and cell cycle arrest at G1 phase in cancer cells." (PMID 33330110, 2020). "CTNNB1 and SHC1 were amplified (0.3% and 22% of patients, respectively), but were not included in the targeted sequencing performed on 173 cancer-related genes in METABRIC." (PMID 32463822, 2020). "Platelet activation, focal adhesion, proteoglycans in cancer, axon guidance, phagosome, glutamatergic synapse and MAPK1, FRS2, FDGFRA, SHC1, ITGB2 and ITGA1 may be the core bio-pathway and genes involved in direct intervention, respectively." (PMID 28380454, 2017). "Pathways such as apoptosis, Myc-mediated apoptosis signaling, SHC1/pSTAT3 signature and TNFR1 signaling were significantly positively correlated with the PANoptosis score across multiple cell types and aligned well with the PA observed in primary tumor clusters via bulk RNA-Seq in SKCM cancer." (PMID 38017056, 2023). "Indeed, nineteen upstream molecular mechanisms and signatures control the way cancers comply or escape to the immune response, including WNT/βCatenin, MAPK, Immunogenic Cell Death, Regulatory T cells, IL23-Th17 axis, PI3K signature, SHC1 signature, IDO/NOS signature and others." (PMID 36224560, 2022). "However, to date, there are no large-scale pan-cancer analyses and systematic studies on the relationship between SHC1 expression and significant clinical outcomes in various tumor types." (PMID 35601500, 2022). "Therefore, we assessed the correlation between SHC1 expression and TMB/MSI in pan-cancer." (PMID 35601500, 2022). "Results indicated that the expression of Tumor-related SHC1 was significantly correlated with the tumor-infiltration of CD8+ T cells, CD4+ T cells, B cells, neutrophils, macrophages, and myeloid dendritic cells in 19, 12, 16, 20, 18, and 17 cancers, respectively." (PMID 35601500, 2022). "For example, the following top 100 MDS genes can be mentioned that are not yet covered by approved or experimental cancer or antineoplastic drugs [according to DrugBank, DGIdb, FDA6, HMDB, Tocris7, GeneCards databases]: GRB2, SOS1,SOS2, SHC1, GNB1, CREB1, GNG2, GNAQ, GNB5, GNAI2." (PMID 30728774, 2019).
tumor (52 papers, 2008 to 2025). "Recent studies have shown that SHC1 is associated with several clinical diseases, especially in tumor development and progression." (PMID 35601500, 2022). "The PLK1, PhosphoMet, SGK2, and SHC1 IHC staining of tumor samples from high-risk (disease progression) patients mostly showed low cytoplasmic expression, while tumor samples from low-risk (progression-free) patients mostly showed high cytoplasmic expression." (PMID 34575686, 2021). "In our analysis, EIF4EBP1, IMP3, ATF3, SEC11A and SHC1 also exhibited different expression between BC and non-tumour samples, and were significantly associated with the tumour type, invasive progression, or tumour grade (SupplementaryFigure S2)." (PMID 34187252, 2021). "Further validation of the FFL (PDGF/FLT1/SHC1) as predictive factor for the survival of the PIK3CA-mutated luminal-A tumor patients is necessary." (PMID 28392480, 2017). "The effect of SHC1 on the tumor-associated macrophage (TAM) infiltration was also assessed." (PMID 35601500, 2022). "It is plausible that numerous tumor intrinsic TKs may be implicated in regulating immunosuppression through Shc1." (PMID 33807608, 2021). "More investigation of the molecular mechanisms of the FFL (PDGF/FLT1/SHC1) in the PIK3CA-mutated luminal-A tumor patients could lead to better predictions and more personalized treatment." (PMID 28392480, 2017). "It similarly revealed that SHC1 overexpression enriched in several tumor-related signaling pathways, including PI-3K/AKT/mTOR and EMT, and in addition, our results suggested that all 3 genes were involved in immune-associated pathways." (PMID 40953006, 2025). "The IHC results showed that ERO1A, CCT6A, and SHC1 were significantly overexpressed in tumor tissues compared to normal samples." (PMID 40953006, 2025). "A comprehensive analysis of multiple oncology databases found that SHC1 plays an important role in the tumour immune microenvironment." (PMID 38632288, 2024). "To identify the potential kinase that associated with SHC1, the phosphorylation of CTNNB1 at Ser552, and the tumor metastasis, we referred to the public database and performed further correlation analysis." (PMID 38360860, 2024). "To further investigate the role of CSNK1G1 in impacting tumor metastasis, we utilized the constructed SHC1-OE-ISOHAS and Ctrl-OE-ISOHAS cells and treated them with the CSNK1G1 inhibitor." (PMID 38360860, 2024). "TIMER2 was employed to estimate the correlations between SHC1 expression and tumor-infiltrating immune cells in the TCGA cohort." (PMID 35601500, 2022). "Using the GTEx dataset as controls and the TCGA data as tumor groups, we discovered an aberrant difference in SHC1 expression between tumor tissues and normal tissues in ACC, DLBC, GBM, PAAD, PCPG, SKCM, and THYM (p < 0.01)." (PMID 35601500, 2022). "CCK8 immunofluorescence staining and EDU experiments showed that compared to controls, overexpression of both IRF7 and SHC1 promoted tumor cell proliferation." (PMID 35692836, 2022). "In tumor tissues, the expression level of SHC1 in the sh-SHC1 group was significantly lower than that in the NC group (P < 0.01)." (PMID 35706930, 2022). "The phosphorylation level of SHC1 increased with the progress of the tumor stage and grade in ccRCC samples." (PMID 35935986, 2022). "Altogether, these results suggest that SHC1 is a potential diagnosis and prognosis biomarker of certain tumors and can play a crucial role in tumor immunity." (PMID 35601500, 2022). "In summary, these findings highlight that SHC1 plays an important role in the tumor immune microenvironment, and SHC1 has been identified to have prognostic and diagnostic value in multiple cancers." (PMID 35601500, 2022). "The results of the bioinformatic analysis were supported by the identification of IRF7 and SHC1 genes as hub IRGs, and the vitro assays demonstrated that IRF7 and SHC1 have a function in promoting tumor progression." (PMID 35692836, 2022).
tumor (continued). "In this present study, we firstly analysed SHC1 expression by using Oncomine, Tumor Immune Estimation Resource (TIMER) and Human Protein Atlas (HPA) databases." (PMID 34117717, 2021). "Among the signature genes we researched, HSPA4, FABP6, S100A10, CACYBP, SHC1 and HDAC1 were associated with a higher tumor grade, CACYBP was linked with a higher clinical stage as well as T stage." (PMID 32191631, 2020). "Some studies have shown that SHC1 downregulates immune surveillance through the RAS/MAPK pathway to promote tumor development." (PMID 33330624, 2020). "Non-genomic activation of membrane ERα has been identified in tumor cells that become hypersensitive to E2 during acquired resistance to hormone deprivation therapies, which appears to be dependent on SHC1 proteins." (PMID 31202267, 2019). "Surprisingly, the recurrence rates of the PIK3CA-mutantation/SHC1-loop+ luminal A tumor patients were lower in the first 5 years after diagnosis than PIK3CA-mutantation/SHC1-loop− luminal A tumor patients (P < 0.01, log-rank test)." (PMID 28392480, 2017). "Statistical analysis also suggested Dnmt3a, Itga6, and Shc1, however high fold changes were measured for these genes in tumor cells." (PMID 21464922, 2011). "The transforming activity of SHC1 has been established, and its overexpression has been reported in neoplasias such as breast, gastric and hepatocelullar carcinomas." (PMID 19055724, 2008). "The upregulation of key regulatory genes in the MAPK pathway, such as MAP2K1, MAP2K2 and SHC1, in tumour cells positive for the three integrin receptors further supports the involvement of the integrin‐MAPK signalling pathway in the functional maintenance of the C0 subpopulation." (PMID 38279519, 2024). "Furthermore, key regulatory genes in the MAPK pathway, such as MAP2K1, MAP2K2 and SHC1, were upregulated in tumour cells positive for the three integrin receptors." (PMID 38279519, 2024). "The higher the tumor stage and grade, the higher the expression of SHC1." (PMID 35706930, 2022). "Taken together, these results suggest that SHC1 plays an essential role in tumor immunity." (PMID 35601500, 2022). "Additionally, the results revealed SHC1 expression was strongly linked to TMB, MMRs, MSI, TAMs, DNA methylation, m6A RNA methylation, tumor-associated immune infiltration, and immune checkpoints in multiple cancers (all p < 0.05)." (PMID 35601500, 2022). "Besides, the phosphorylation level of SHC1 increased with the progress of the tumor stage and grade in CPTAC-ccRCC samples." (PMID 35935986, 2022). "In addition, we also found that overexpression of EGFR and SHC1 promoted the expression of tumor-related transcription factors." (PMID 35706930, 2022). "Tumor results also showed that the tumor weight decreased after SHC1 silencing." (PMID 35706930, 2022). "The detection of SHC1 methylation at specific probes in tumour tissues from LUAD and LUSC patients may help detect tumorigenesis at early stage." (PMID 34117717, 2021). "Thus, we can stratify patients into high-risk groups and rapidly assess their outcomes based on the tumor expression of cytoplasmic PLK1, phosphoMet, SGK2, and SHC1." (PMID 34575686, 2021). "Therefore, radiotherapy-resistant cell lines may overexpress SHC1 to mediate elevated levels of autophagy and thus contribute to the survival of tumor cells after irradiation by affecting radiotherapy sensitivity, resulting in radiotherapy resistance." (PMID 36311724, 2022). "SHC1 may play a tumor-promoting role by regulating EGFR signaling pathway." (PMID 35706930, 2022). "Targeting SHC1 may have a synergistic effect with immunotherapy to eradicate tumor cells." (PMID 35935986, 2022). "Moreover, SHC1 was downregulated by miR-5582-5p, thus led a tumor suppressive activity with GAB1." (PMID 33936170, 2021). "We then treated SHC1-OE-ASM and OE-Ctrl-ASM (transfected with empty vectors as the control) with TGFB3 and evaluated the tumor cell migration rates." (PMID 38360860, 2024).
tumor (continued). "We found that MAP2K6, MAP3K5, MAP3K9, MAP3K12, RPS6KA2, RPS6KA5, and STAT1 were lowly expressed in tumor tissues; However, NFKB1, RAC1, SHC1, and TRAF2 are highly expressed compared to normal tissues." (PMID 36969076, 2023). "We found that TGFA, SHC1, PIK3CD, GAB1, and AKT3 were negatively correlated with six tumor immune cells in KIRC, and EIF4EBP1 was positively correlated with macrophage infiltration." (PMID 35903358, 2022). "Among them, SHC1, FKBP4, NRAS, KRAS had higher expression, and PRKCD, ADCY9 had lower expression in LUAD tumor tissues compared with normal tissue." (PMID 33936178, 2021). "In line with this, targeting the pathways closely upstream or downstream of Shc1 (e.g., ErbB2, EGFR, MEK, ERK, PTEN, PI3K) by drugs or molecular manipulation has been shown to enhance anti-tumor immune responses in various studies, as discussed later." (PMID 33807608, 2021). "GEO datasets validated that the 6 genes (SHC1, FKBP4, NRAS, PRKCD, KRAS, ADCY9) had different expression between tumor tissues and adjacent normal tissues in LUAD, and 3 genes (FKBP4, KRAS, ADCY9) were related to the prognosis of LUAD." (PMID 33936178, 2021). "We found ten potential prognostic genes, including eight tumor suppressor and/or driver genes (VEGFA, CCND1, BAX, IL7R, SHC1, FLT1, IL7, and JAK3), as well as two chemokines (CXCL9 and CXCL10)." (PMID 31661791, 2019). "GRB2 interaction with SHC1 (pY439 and pY427) has been shown in T cells to induce Ras-Erk signaling and CD69 leading to tumor cell survival and promoting tumor vascularization." (PMID 23826330, 2013). "Notably, LDHA, SHC1, and EPHX1 exhibited heightened expression levels in tumor tissues, while MYO6 and TLE1 displayed diminished expression compared to normal tissues." (PMID 37965333, 2023). "Of the 398 IHC pairs, multivariate Cox regression analyses showed that CSNK1E↓-SHC1(N)↓, CSNK1E↓-RB1(N)↑, and BRCA1(N)↓-SHC1(N)↓ were significant predictors of the risk of death in this Taiwanese OSCC population, independent of tumor stage." (PMID 33936170, 2021). "These cell lines stem from disparate tumor or tissue types, but they were all predicted to have very high recruitment of CRKL (more than one copy of CRKL bound to each molecule of IGF1R) coupled with moderately high recruitment of either SRC, SHC1, or RASA1." (PMID 30653502, 2019). "We next asked whether inactivating other mTORC1 components in C. elegans, let-363/TOR, rheb-1/Rheb, and daf-15/Raptor, could also suppress the shc-1;Is[daf-16::GFP] tumor." (PMID 28549065, 2017). "Notably, genes such as SHC1 and PTK6 regulate essential signal transduction pathways, including the MAPK and PI3K cascades, which are critical for both tumour cell proliferation and resistance to programmed cell death—mechanisms that have been strongly implicated in therapeutic resistance in ccRCC." (PMID 40830065, 2025). "Besides, the SHC1 mRNA expression tends to be increased in tumor tissues compared with the adjacent non-tumor tissues." (PMID 38602568, 2024). "Interestingly, in our present study, SHC1 was an important hub IRGs in the PPI network, suggesting that SHC1 may play a general broad-spectrum function in tumor progression." (PMID 35692836, 2022). "In addition, IRF7 and SHC1 were hub IRGs in PPI network, and the vitro assays proved that they could promote tumor progression." (PMID 35692836, 2022). "Moreover, we investigated the relationship between SHC1 expression and TMB, MMRs, MSI, DNA methylation, m6A RNA methylation, protein phosphorylation, tumor immune infiltration, common immune checkpoint, and tumor-associated macrophage (TAM) from the related public websites." (PMID 35601500, 2022). "Furthermore, as the RTK binding protein Shc1 is established to mediate angiogenesis via VEGF-A-dependent signaling and SHCBP1 interacts with phosphorylated SHC1, the SHC–SHCBP1 axis may indirectly facilitate vascular remodeling in tumor contexts." (PMID 41009347, 2025).
tumor (continued). "As a result, SHC1-OE-ASM treated with TGFB3 showed significantly elevated tumor cell migration rates, whereas OE-Ctrl-ASM showed no significantly changes in tumor cell migration rates after treated with TGFB3." (PMID 38360860, 2024). "A small network of downregulated genes was found in tumor cells, in which EGF and beta-c interact with Shc and a complex comprising EGF, ErbB1, Shc-1, Grb2, and Sos (not shown)." (PMID 21464922, 2011).
infection (4 papers, 2012 to 2018). The state of being infected such as from the introduction of a foreign agent such as serum, vaccine, antigenic substance or organism. "Tarp phosphorylation also leads to interaction with the SHC1 signaling initiator, which modulates native apoptosis and promotes post-infection survival." (PMID 29386631, 2018). "Likewise, the Trefoil Factor Initiated Mucosal Healing pathways were significantly suppressed in early stage of infection, more specifically, PTK2, GHR, RHOA, CTNNB1, MAPK3, and SHC1 genes." (PMID 24349118, 2013).
nervous system disease (1 paper, 2025). "Recent literature supports the SHC1 with nervous system disease." (PMID 40537751, 2025).
SHC1 also shares sentences with these, for which no sentence is quoted: Obesity (5 papers); prostate carcinoma (3); cardiovascular diseases (2); glioblastoma (2); kidney cancer (2); lung squamous cell carcinoma (2); rheumatoid arthritis (2); Alzheimer disease (1); astrocytic tumor (1); Azoospermia (1); brain tumor (1); cardiac arrest (1); cholangiocarcinoma (1); choroid plexus tumors (1); coronary heart disease (1); dilated cardiomyopathy (1); ectodermal dysplasia (1); embryonal tumors (1); endothelial dysfunction (1); ependymal tumor (1); escherichia coli infection (1); esophageal squamous cell carcinoma (1); focal segmental glomerulosclerosis (1); gastrointestinal tumor (1); glaucoma (1); head and neck cancer (1); Hyperinsulinemia (1); Hypertension (1); inflammatory bowel disease (1); Insulin resistance (1).
A further 19 diseases each share a sentence with SHC1 in 1 paper.